DAZ4 (deleted in azoospermia 4)
Description:
RNA-binding protein that plays an essential role in spermatogenesis. May act by binding to the 3'-UTR of mRNAs and regulating their translation.
Synonyms: pDP1680; pDP1681
Tractability: PROTAC: ubiquitination databases record sites on it.
Gene: Protein-coding gene on chromosome Y (24,833,843 to 24,907,040, forward strand). Ensembl gene ENSG00000205916.
Subcellular location: Cytoplasm; Nucleus
Gene Ontology:
Molecular function: protein binding; translation activator activity; mRNA 3'-UTR binding; nucleic acid binding; RNA binding
Biological process: 3'-UTR-mediated mRNA stabilization; positive regulation of translational initiation
Cellular component: cytoplasm; protein-containing complex; nucleus
Homologues: Orthologues: dog DAZL (27% identical), guinea pig DAZL (23% identical), tropical clawed frog dazl (16% identical), zebrafish dazl (12% identical), Caenorhabditis elegans daz-1 (10% identical), Drosophila melanogaster bol (8% identical). Paralogues in human: DAZ1 (79% identical), DAZ2 (77% identical), DAZ3 (60% identical), DAZL (25% identical), BOLL (11% identical).
Diseases named in the same sentence as DAZ4 in open-access papers:
DAZ4 is named in the same sentence as 4 diseases in open-access papers, as found by Europe PMC text mining. Sharing a sentence is not in itself a finding about the gene and the disease. The quoted sentences say what the papers report.
male infertility (5 papers, 2021 to 2025). The inability of the male to effect fertilization of an ovum after a specified period of unprotected intercourse. "Moreover, we investigate the Y-chromosome genes, DAZ1/DAZ2/DAZ3/DAZ4, of which structural variants have been linked to male infertility, and X-chromosome genes OPN1LW and OPN1MW linked to eye disorders." (PMID 37365340, 2023). "The loss of the deleted in azoospermia (DAZ) genes DAZ1, DAZ3, and DAZ4 leads to spermatogenic arrest, contributing to male infertility." (PMID 40391511, 2025).
Infertility (1 paper, 2025). "Some infertility-related genes were identified in these networks, including DAZ family genes (DAZ1, DAZ3, and DAZ4), NF1 family TF motifs (NFIX), and ras association domain family 8 (RASSF8)." (PMID 40391511, 2025).
DAZ4 also shares sentences with these, for which no sentence is quoted: Azoospermia (3 papers); oligospermia (1).